HOXA9 (homeobox A9)
Diseases named in the same sentence as HOXA9 in open-access papers (continued):
Sharing a sentence is not in itself a finding about the gene and the disease.
prostate carcinoma (9 papers, 2018 to 2024). A carcinoma that arises from epithelial cells of the prostate gland. "By forming a protein complex with TWIST1, WDR5 induces HOXA9 gene transcription, prostate cancer cell migration, invasion, and metastasis." (PMID 30488017, 2018). "Twist1 regulates WDR5-Hottip-mediated Hoxa9 chromatin to promote prostate cancer metastasis." (PMID 36639679, 2023). "Moreover, HOTTIP modulates cancer stem cell properties by binding WDR5 and activating HOXA9, which enhances the Wnt/β-catenin pathway in prostate cancer stem cells." (PMID 30819158, 2019). "In addition, TWIST1 and HOXA9 are enriched in primary human prostate cancer tissues and even further over-expressed in metastatic tissues." (PMID 30488017, 2018). "It has been reported that during the progression of prostate cancer (PCa), aberrantly expressed HOXA2, HOXA9, and HOXA10 facilitate the infiltration of dendritic cells, macrophages, and mastocytes." (PMID 38904676, 2024). "HOXA13, HOXA1, HOXA5, HOXA6, HOXA7, HOXA9, and HOXA10 are involved in prostate cancer, and they form a DNA loop with a locus that induces prostate cancer and regulates gene transcription." (PMID 37590265, 2023). "In another study on prostate cancer, HOXA2, HOXA9, and HOXA10 were identified as critical genes, which were both abnormally expressed and associated with clinical outcomes of patients with prostate cancer." (PMID 36159969, 2022). "In prostate cancer, HOTTIP forms a complex with the transcription factor TWIST1 and with WDR5 and produces upregulation of HOXA9 levels through chromatin regulation which correlates with an aggressive cellular phenotype." (PMID 30819158, 2019).
meningioma (7 papers, 2013 to 2024). A generally slow growing tumor attached to the dura mater. "Within the PCR-targeting genes, DNA hypermethylation of HOXA6 and HOXA9 has also been implicated in recurrent meningiomas according to another study." (PMID 23349797, 2013). "Similar to TIMP3, repression of HOXA7, HOXA9, and HOXA10 in meningioma is also associated with clinically aggressive behaviour." (PMID 26101774, 2015). "For this purpose, 44 WHO grade I meningiomas, including 8 showing regrowth after radiosurgery, were analysed for Ki-67 and NDRG4 protein expression, loss of 1p36 and promotor hypermethylation of the genes NDRG1-4, SFRP1, HOXA9 and MGMT." (PMID 34385566, 2021). "DNA methylation levels of HOXA7, HOXA9, and HOXA10 were reported to be significantly higher in atypical and anaplastic meningiomas than in the benign form." (PMID 26101774, 2015). "DNA methylation levels of HOXA7, HOXA9 and HOXA10 were reported significantly higher in WHO grade II and III meningiomas than in grade I (benign) meningiomas." (PMID 23349797, 2013). "Genes with hypermethylated CpG islands in malignant meningiomas (such as HOXA6 and HOXA9) tend to coincide with the binding sites of polycomb repressive complexes (PRC) in early developmental stages." (PMID 23349797, 2013). "For the malignant meningiomas in our study, 26 genes were identified as significantly hypermethylated at promoter CpG islands, including eight genes involved in the biological pathway of neurogenesis (BARHL2, TLX3, FOXR1, HOXA11, HOXA6, HOXA9, OTX2 and PAX3)." (PMID 23349797, 2013). "MSP for NDRG1-4, SFRP1, HOXA9 and MGMT was performed on 41 meningioma samples and 10 nontumoral control brain tissue samples." (PMID 34385566, 2021).
myeloproliferative neoplasm (7 papers, 2013 to 2022). A clonal hematopoietic stem cell disorder, characterized by proliferation in the bone marrow of one or more of the myeloid (i.e., granulocytic, erythroid, megakaryocytic, and mast cell) lineages. "Hoxa9 overexpression alone in mouse bone marrow cells leads to a myeloproliferative disorder that progresses to AML around 7 months, suggesting the requirement for additional genetic events prior to AML." (PMID 36285442, 2022). "Hoxa9 overexpression alone in mouse bone marrow leads to a myeloproliferative disorder." (PMID 36285442, 2022). "Here, the authors show that HOXA9 has a binary switch function that can clinically stratify AML patients, and model how the interactions with JAK2, TET2 and NOTCH impact myeloproliferative neoplasms." (PMID 36192425, 2022). "Here, we highlight the biological switch and prognosis marker properties of HOXA9 in AML and chronic myeloproliferative neoplasms (MPN)." (PMID 36192425, 2022).
squamous cell carcinoma (7 papers, 2007 to 2025). A carcinoma arising from squamous epithelial cells. "The low-methylation epigenotype of HOXA2 and HOXA9 in squamous cell carcinoma was associated with idiopathic pulmonary fibrosis and poorer prognosis." (PMID 36159969, 2022). "Our analysis has revealed that histology, specifically squamous cell carcinoma, is significantly associated with the hypermethylation of both SOX1 and HOXA9." (PMID 40699796, 2025). "Decreased expressions of HOXA9 in non- melanoma skin cancer, including squamous cell carcinoma than control skin were registered." (PMID 39462379, 2024). "High methylation percentage of HOXA9 has been reported in early stages of primary squamous cell carcinomas of the lung." (PMID 17623056, 2007). "Furthermore, HOXA9 methylation levels showed to be higher in squamous cell carcinoma in comparison with adenocarcinoma in study group #1." (PMID 31546933, 2019).
cutaneous squamous cell carcinoma (6 papers, 2018 to 2022). "In contrast, onco-miR-365 expressed in cutaneous squamous cell carcinoma abolishes the Homeobox A9 (HOXA9)-mediated downregulation of HIF-1α, along with HK2, GLUT1 and PDK1, thereby enhancing glycolysis." (PMID 33806538, 2021). "Tumor suppressor HOXA9 has been identified to promote apoptosis in cutaneous squamous cell carcinoma (cSCC)." (PMID 31683603, 2019). "Here the authors show, using both cell lines and animal models, that in cutaneous squamous cell carcinoma HOXA9 acts as a tumor suppressor and inhibits glycolysis by associating with CRIP2 to repress HIF-1α binding to target genes." (PMID 29662084, 2018). "However, HOXA9 is down-regulated in cutaneous squamous cell carcinoma (cSCC), which means that the miR-365-HOXA9-HIF-1α axis promotes glycolysis." (PMID 33109235, 2020). "For example, miR-365 directly targets homeobox A9 (HOXA9) by binding to 3′-UTR region, and the downregulation of HOXA9 increases the expression of HIF-1α and its downstream glycolytic genes HK2, GLUT1, and PDK1, promoting glycolysis and metastasis of cutaneous squamous cell carcinoma." (PMID 32547948, 2020).
hepatocellular carcinoma (6 papers, 2013 to 2024). A malignant tumor that arises from hepatocytes. "HOXA9 methylation occurred in hepatocellular carcinoma tissues which might be a useful biomarker in detection of hepatocellular carcinoma." (PMID 36376832, 2022). "However, studies have shown that HOXA9 hypermethylation promotes hepatocellular carcinoma development, suggesting that HOXA9 may have different roles in different cancer types." (PMID 38285101, 2024).
melanoma (6 papers, 2017 to 2024). A malignant, usually aggressive tumor composed of atypical, neoplastic melanocytes. "HOXA9 methylation is also a validated biomarker for cutaneous melanoma progression, with high methylation in metastases but low methylation in primary melanoma and nevi." (PMID 38336771, 2024). "In one study, researchers identified and validated biomarkers for melanoma development (HOXA9 DNA methylation) and tumor progression (TBC1D16 DNA methylation)." (PMID 31395792, 2019). "A comprehensive DNA methylation study of melanomas at various stages of development identified some genes specifically involved in tumor development (HOXA9) or progression (TBC1D16)." (PMID 29156643, 2017). "We identified and validated biomarkers for, and pathways involved in, melanoma development (e.g., HOXA9 DNA methylation) and tumor progression (e.g., TBC1D16 DNA methylation)." (PMID 28578692, 2017).
oral cancer (6 papers, 2014 to 2026). "The epigenetic alterations of some genes, such as HOXA9, have been implicated in both oral cancer and esophageal cancer patients as potential biomarkers for the early detection of the field of cancerization." (PMID 28562351, 2017). "HOXA9 methylation is frequent in oral cancers and levels are higher in tumors with greater risk of metastasis." (PMID 24886209, 2014). "While we show here that HOXA9 also appears to positively regulate BRCA1 expression in oral cancer cells, further studies will be required to fully understand how HOXA9 functions as a tumor suppressor in oral cancer." (PMID 24886209, 2014). "Re-expression of HOXA9 in the SCC4 oral cancer cell line resulted in diminished proliferation and colony formation." (PMID 24886209, 2014). "In oral cancer cell lines with nearly complete methylation of the HOXA9 promoter, HOXA9 expression levels are low." (PMID 24886209, 2014). "The HOXA9 promoter is nearly completely methylated in oral cancer cell lines and to a slightly lesser extent in DOX, a cell line derived from dysplastic tissue." (PMID 24886209, 2014). "Pbx2 and hypermethylation of Meis1 and HoxA9, however, may be considered prognostic markers of oral cancer." (PMID 33402862, 2020). "Our data are consistent with HOXA9 acting as a tumor suppressor in oral cancer." (PMID 24886209, 2014).
cervical cancer (5 papers, 2017 to 2024). A primary or metastatic malignant neoplasm involving the cervix. "The expression of Hoxa9 is required for normal cervical physiology and some cervical cancer cells have shown a downregulation of Hoxa9 expression, which is modulated by both methylation and HPV infection." (PMID 33402862, 2020). "Notably, research on cervical cancer (CC) revealed that the repression of HOXA9 results from increased methylation of its first exon." (PMID 38904676, 2024). "Moreover, targeting the human oncogene B-cell-specific moloney murine leukemia virus integration site 1 in the cervical cancer cell line leads to Hoxa9 activation." (PMID 33402862, 2020). "Moreover, low expression of this marker was observed in cervical cancer cells and proliferation and migration were suppressed when HOXA9 expression was restored in these cells." (PMID 31043660, 2019). "On the other hand, another study showed that Hoxa9 was expressed in both cervical carcinoma cell lines and normal cervical tissues." (PMID 33402862, 2020).
myeloma (5 papers, 2014 to 2023). "Intracellular miR-365 is overexpressed in myeloma tissues and induces apoptosis and inhibits metastasis by modulating homeobox A9 (HOXA9)." (PMID 37048103, 2023). "Recent sequencing observed that HOXA9 was ubiquitously expressed across 38 myeloma samples and hypothesised whether this gene represented a candidate oncogene." (PMID 24803933, 2014). "Specifically, we found that healthy MSCs exposed to MM cells underwent gains (HOXA9, ACVR2A, EBF2) and losses (HOXA2, HOXA3, HOXC5) of DNA methylation in the direction of those observed for MSCs from myeloma patients." (PMID 33462210, 2021). "Other genes involved in methylation and chromatin modification are also deregulated in myeloma, including KDM6A, MLL genes and HOXA9." (PMID 24803933, 2014). "Immunomodulatory imide drugs (IMiDs), which have FDA approval for treatment of multiple myeloma and myelodysplastic syndrome, degrade IKAROS and disrupt the expression of HOXA9 target genes without affecting HOXA9 expression itself." (PMID 38174649, 2023).
endometriosis (4 papers, 2018 to 2025). The growth of functional endometrial tissue in anatomic sites outside the uterine body. "The endometriosis risk allele G rs440837 reduces affinity for the TF Hoxa9 (the difference in the “LODscores” parameter of the G and A alleles was −1.7) and increases sensitivity to TFs Hlx1 and Smad3 (differences in the “LODscores” of the G and A alleles are 1.5 and 7.5, respectively)." (PMID 41373783, 2025). "WNT4 was shown to be expressed in the normal peritoneum, suggesting that endometriosis can arise through a reversible transformation of the epithelium cells to endometriotic cells (metaplasia) through the developmental pathways associated with the HOXA9 and CDKN1A genes." (PMID 29937493, 2018). "Based on our findings, we propose that two molecular mechanisms are involved in endometriosis pathogenesis, where, firstly, HOXA9 and HOXA10 genes are regulated by miR-139-5p among other factors and are potentially involved in endometriosis-associated infertility." (PMID 30487429, 2018).
esophageal cancer (4 papers, 2017 to 2025). A primary or metastatic malignant neoplasm involving the esophagus. "Although HOXA9, a member of the HOX gene family, is implicated in various malignancies, its specific inclusion in methylation panels for cervical or esophageal cancer is less well documented." (PMID 40699796, 2025). "Additionally, HOXA9 binds to microRNA-186-5p to inhibit the proliferation and metastasis of esophageal cancer." (PMID 37393256, 2023).
laryngeal squamous cell carcinoma (4 papers, 2022 to 2024). A squamous cell carcinoma that arises from the larynx. "The m6A demethylase ALKBH5-mediated m6A modification of lncRNA KCNQ1 overlapping transcript 1 promotes the proliferation, invasion, and metastasis of laryngeal squamous cell carcinoma cells by upregulating HOXA9." (PMID 36982798, 2023). "HOXA9 acted as a cancer promoter in head and neck squamous cell carcinoma (HNSCC) and laryngeal squamous cell carcinoma to promote the proliferation and migration of cancer cells." (PMID 38605318, 2024).
myeloid malignancies (4 papers, 2015 to 2022). "In myeloid malignancies, HOXA9 upregulates MSI2, and MSI2 then downregulates NUMB, a negative regulator of NOTCH, thereby promoting cell division during blast crisis." (PMID 33504942, 2021).
anemia (3 papers, 2017 to 2025). A reduction in the number of red blood cells, the amount of hemoglobin, and/or the volume of packed red blood cells. "Bidirectional Effects on Erythropoiesis: While ASXL1 truncations repress erythroid differentiation via GATA1/KLF1 silencing (contributing to anemia), concomitant H3K27me3 loss at proliferative loci (e.g., HOXA9) may paradoxically expand early erythroid progenitors." (PMID 40772034, 2025).
breast tumor (3 papers, 2013 to 2022). "Mechanistically, HOXA9 inhibited breast tumor malignant behavior through modulating BRCA1 expression." (PMID 36376832, 2022).
cardiac hypertrophy (3 papers, 2020 to 2022). "Since the regulatory role of HoxA9 in cardiac hypertrophy was uncertain, gain-of-function and loss-of-function experiments were designed to investigate the effect of HoxA9 in NRCMs." (PMID 33424610, 2020). "In cardiomyocytes, PRMT5 symmetrically dimethylates HoxA9 and inhibits HoxA9 expression, preventing binding to promoters and protecting cardiomyocytes from cardiac hypertrophy." (PMID 35855865, 2022). "PEG10 can regulate the expression of homeobox A9 (HOXA9) to aggravate cardiac hypertrophy; the silence of HOXA9 reverses the cardiac hypertrophy in cardiomyocytes by over-expressing PEG10." (PMID 35269399, 2022). "The lncRNA UCA1 can promote the progression of cardiac hypertrophy as an endogenous sponge of miR-184 to enhance the expression of HOXA9." (PMID 35269399, 2022). "Our preliminary studies showed that there were interactions between PRMT5 and HoxA9 in pathological cardiac hypertrophy and that HoxA9 was involved in the regulation of PRMT5 in cardiomyocyte hypertrophy." (PMID 33424610, 2020). "The results are in line with those in vivo data, confirming that HoxA9 was upregulated while PRMT5 was downregulated in ISO-induced cardiac hypertrophy." (PMID 33424610, 2020). "Our study confirmed that HoxA9 expression was augmented by β-adrenergic stimulation during cardiac hypertrophy." (PMID 33424610, 2020). "Although previous studies have reported that HoxA9 was upregulated during cardiac hypertrophy, the exact regulatory role of HoxA9 in cardiac hypertrophy remains to be elucidated." (PMID 33424610, 2020). "Recent studies have revealed that HoxA9, a member of HoxA cluster genes, was downregulated in hypertensive patients, and that mRNA level of HoxA9 was enhanced in cardiac hypertrophy." (PMID 33424610, 2020). "The novel finding of our study is that PRMT5 could ameliorate cardiac hypertrophy via HoxA9." (PMID 33424610, 2020). "Most importantly, our results demonstrated that HoxA9 could bind to the promoters of BNP and β-MHC, two typical cardiac hypertrophic markers, suggesting that HoxA9 serves as a transcription factor of BNP and β-MHC to facilitate the development of cardiac hypertrophy." (PMID 33424610, 2020).
colorectal tumor (3 papers, 2008 to 2024). "In summary, our analysis of clinical samples confirmed the downregulation of miR-140-3p and the upregulation of HOXA9 in colorectal tumor tissues." (PMID 38285101, 2024). "MiR-140-3p was significantly downregulated in colorectal tumors compared to normal tissue, and HOXA9 was identified as a previously unreported potential downstream target." (PMID 38285101, 2024). "On the other hand, mir133b downregulates Hoxa9 expression and inhibits colorectal tumor cell proliferation and migration." (PMID 33402862, 2020). "Hoxa9 mRNA and protein expression were reported as increased in colorectal tumor tissues when compared with normal tissues and elevated Hoxa9 expression was correlated with lymph node metastasis." (PMID 33402862, 2020). "Members of the HOX gene family are shown to be commonly altered in several cancers, and to the best of our knowledge, this is the first report of HOXA9 methylation in colorectal neoplasms." (PMID 19117505, 2008).
head and neck squamous cell carcinoma (3 papers, 2022 to 2024). A squamous cell carcinoma that arises from any of the following anatomic sites: lip and oral cavity, nasal cavity, paranasal sinuses, pharynx, larynx, and salivary glands. "HOXA9 as an oncogene upregulated in Head and neck squamous cell carcinoma (HNSCC) is also reported to be related with HIF-1a signaling pathway." (PMID 36376832, 2022).
lymphoma (3 papers, 2020 to 2023). A malignant (clonal) proliferation of B- lymphocytes or T- lymphocytes which involves the lymph nodes, bone marrow and/or extranodal sites. "This link may suggest that overexpression of HOXA9 or c-MYB is present in a subset of DLBCL, predicting aggressive behavior probably through the expression of a stemness phenotype by lymphoma cells." (PMID 33288848, 2020).
malignant glioma (3 papers, 2015 to 2018). A grade III or grade IV glioma arising from the central nervous system. "HOXA9 and HOXA10 genes were associated with a shorter survival in pediatric high-grade glioma patient samples, while elevated HOXA9 and HOXA10 gene methylation was associated with an increased survival probability." (PMID 28055976, 2017). "Specifically, it was shown that HOXA9 and HOXA10 have prognostic value in adult and pediatric high-grade glioma patients." (PMID 25762636, 2015).
ovarian tumor (3 papers, 2011 to 2021). "In that sense, HOXA9 hypermethylation has been described in ovarian tumours and in squamous cell lung carcinomas." (PMID 21603610, 2011).
Pancytopenia (3 papers, 2012 to 2019). An abnormal reduction in numbers of all blood cell types (red blood cells, white blood cells, and platelets). "Furthermore, mice with AML induced by co-expression of BCR/ABL and the Nup98/HoxA9 fusion protein showed a loss of osteolineage cells in the marrow, which may have contributed to the underlying pancytopenia." (PMID 22952867, 2012). "HoxA9 is co-expressed with additional HoxA proteins, in particular HoxA5, HoxA7, and HoxA10, in immature hematopoietic populations, which likely accounts for the observation that HoxA9-/- mice manifest only mild pancytopenia." (PMID 31120998, 2019). "Of note, sublethally irradiated Hoxa9-/- mice exhibited prolonged suppression of hematopoiesis and developed persistent pancytopenia, indicating an enhanced sensitivity to ionizing irradiation in t-AML cells with deficient HOXA9." (PMID 26043758, 2015).